ALB (albumin)
Diseases named in the same sentence as ALB in open-access papers (continued):
Sharing a sentence is not in itself a finding about the gene and the disease.
Obesity (continued). "While studies have shown that plasma composition with respect to serum albumin and hematocrit are largely unaffected by obesity, it changes with respect to α1-acid glycoprotein (AAG), which increases approximately 2-fold with obesity in adults." (PMID 35359853, 2022). "Among the 6 independent factors identified, most were repeatedly investigated in literature, such as delay to admission or DVT screening, higher BMI or obesity, peripheral vascular disease, reduced albumin and elevated D-Dimer level." (PMID 35509097, 2022). "The hemoglobin (average 11.86 g/dL) and serum albumin (median 3.8 mg/L) concentrations were also lower than patients with physiological non-obesity." (PMID 36324141, 2022). "Fourth, this study focused only on the muscle quantity to explain the obesity paradox, excluding serologic tests such as C‐reactive protein or albumin." (PMID 35212195, 2022). "Patients with and without tracheal stenosis had similar clinical features, with only minor differences in body mass index, incidence of obesity, and serum albumin levels." (PMID 34991555, 2022). "Echocardiography information of study participants according to obesity and serum albumin categories." (PMID 34061848, 2021). "The study aimed to evaluate the urinary excretion of albumin, α1-AGP, and mRNA of podocyte-specific proteins as indicators of glomerular injury in obese children and their association with the degree of obesity SDS BMI reference ranges and metabolic disorders." (PMID 34575240, 2021). "In this review, we summarize the evidence supporting the role of overweight- and obesity-induced oxidative stress as a critical factor for the progression of renal disease and cardiovascular morbimortality through albumin oxidation." (PMID 33800425, 2021). "This study shows in vitro the effects of digested proteins from chia seed, including total protein and its fractions, albumin and glutelin, on adipogenesis and inflammation of adipose tissue, markers of obesity and its complications." (PMID 33430086, 2021). "The applied concentration of both fatty acids, PA and OA, has previously been used in other in vitro studies, and the used BSA concentration relates to serum albumin and is characteristic for obesity and hypertriglyceridemia." (PMID 34199865, 2021). "Among 26 tested variables, 7: obesity, cardiovascular conditions, plasma sodium, albumin, ferritin, LDH and CK were the independent predictors of severity used in Covichem (accuracy 0.87, AUROC 0.91)." (PMID 33956870, 2021). "Indices such as the prognostic nutritional index (PNI), albumin, BMI, and obesity have been well studied, and there is considerable evidence for their prognostic effects." (PMID 35127536, 2021). "After multivariate analysis, only albumin rate ≤ 35 g/L increased post operative morbidity (p = 0.007) and there was just a tendency of increase with obesity (BMI 25–30, p = 0.642)." (PMID 32107426, 2020). "Risks factors of developing CUA among dialysis patients were obesity, VKA, weight loss, serum albumin decrease or high serum phosphate in the 6 months before lesion onset." (PMID 32101140, 2020). "Multivariate analyses identified obesity, delay to admission, increased D-dimer level (> 1.44 mg/L) and reduced albumin (< 31.7 g/L) as independent factors." (PMID 33213498, 2020). "The multivariate regression analysis showed that obesity, delay to admission, increased D-dimer level (> 1.44 mg/L), and reduced albumin (< 31.7 g/L) were identified as independent factors associated with DVT." (PMID 33213498, 2020). "Obesity-related renal disease involves a wide spectrum of disorders, from excretion of urinary albumin to proteinuria and/or decreased GFR." (PMID 30145854, 2019). "Age, preoperative estimated glomerular filtration rate (eGFR), hemoglobin, albumin, proportion of moderate or severe LV dysfunction, atrial fibrillation, and obesity were significantly different among patients with CAD, AS, and MR." (PMID 29420603, 2018).
Obesity (continued). "Obesity, pulmonary disease, low serum albumin level, and classes III and IV in ASA score were the main patient-dependent factors contributing to skin superficial and deep incisional SSIs." (PMID 27650707, 2016). "This is found both in obese adults and children and lower than expected glycated albumin in obesity also extends into the patients with T2DM." (PMID 27338619, 2016). "Severe obesity compared with milder obesity status cannot predict the occurrence of increased urinary albumin excretion and microalbuminuria." (PMID 26060835, 2015). "The role of IL-22 in regulating obesity and metabolic syndrome was further examined in IL-22 transgenic mice, in which IL-22 expression is controlled by albumin promoter and enhancer." (PMID 26064446, 2015). "Indexes of additive biological interactive effect of obesity and central obesity on elevated urinary albumin-to-creatinine ratio." (PMID 24892930, 2014). "Odd Ratios and 95% confidence intervals of elevated urinary albumin-to-creatinine ratio with obesity." (PMID 24892930, 2014). "Both additive and multipliable interactions between obesity and central obesity on elevated urinary albumin-to-creatinine ratio (UACR) were evaluated." (PMID 24892930, 2014). "Interactive effect analysis of obesity and central obesity on elevated urinary albumin-to-creatinine ratio." (PMID 24892930, 2014). "Urinary albumin/creatinine ratio (ACR) was increased in the obesity group compared to controls (P < 0.01)." (PMID 23710462, 2013). "Expression of the human N-terminal transcriptionally active domain of SREBP-1c under the control of the liver-specific albumin promoter in mice induces a mild fatty liver and an obesity phenotype." (PMID 22363740, 2012). "Commonly associated conditions in the pathogenesis of calciphylaxis include obesity, hyperphosphatemia, an elevated calcium-phosphate product, secondary hyperparathyroidism, high alkaline phosphatase and low serum albumin." (PMID 18811973, 2008). "We aimed to investigate the concordance between ACR and 24‐h urinary albumin excretion (UAE) in adults with obesity and examine whether discrepancies affect the detection of vascular dysfunction." (PMID 40557880, 2025). "At the same time, our study highlights an association between BFRs and inflammation and oxidative stress markers, such as lymphocyte and albumin, which may explain BFRs link to obesity." (PMID 40350287, 2025). "This may be due to MGO accumulation in fat tissue and a plasma-to-interstitial shift of albumin in obesity." (PMID 40864317, 2025). "Additionally, the presence of uric acid and albumin further supports the potential involvement of inflammation and oxidative stress in the pathology of obesity, a direction that has gained widespread attention in recent years." (PMID 40917432, 2025). "While obesity-driven inflammation contributes to myocardial remodeling, albumin's anti-inflammatory and endothelial-stabilizing properties, combined with lymphocyte-mediated immune surveillance, may counteract these processes in individuals with optimal PNI." (PMID 40630165, 2025). "This aligns with previous suggestions that unhealthy lifestyle factors (such as smoking and obesity) and metabolic dysregulation can contribute to systemic inflammation, consequently influencing both neutrophil and albumin levels, and ultimately affecting NPAR." (PMID 41327740, 2025). "Changes in albumin may reflect subclinical inflammation, oxidative damage, or early renal impairment in obesity." (PMID 40943443, 2025). "Insulin resistance, a common feature of obesity, could increase the levels of serum-free fatty acids, competing with tryptophan for binding to serum albumin." (PMID 39780112, 2025). "Values of serum ALB has been reported to be decreased in obesity." (PMID 38703299, 2024).
Obesity (continued). "A thorough search of the PubMed database was conducted for our review, specifically targeting studies that investigate several aspects impacting postoperative outcomes, including nutritional status, obesity, albumin levels, sodium levels, fluid management, and psychological well-being." (PMID 39459466, 2024). "It’s hard to imagine obesity leading to a decrease in albumin levels." (PMID 39287227, 2024). "Obesity induces an increase in metabolic demand, which in the kidney promotes glomerular hyperfiltration, tubulomegaly, and increased reabsorption of solutes (sodium, glucose, albumin, etc.)." (PMID 37629165, 2023). "Also, the median albumin concentration in patients with a normal BMI was significantly higher than in those with high BMI values indicative of overweight and obesity (34.3 mg/mL vs. 18.4 mg/mL vs. 14.8 mg/mL, respectively, p = 0.0251)." (PMID 37571416, 2023). "Serum albumin may facilitate aspects of metabolic dysregulation in obesity because of its involvement in inter-organ FFA transport." (PMID 37432201, 2023). "After adjusting for age (continuous), gender, race, education, smoking status, alcohol consumption, Obesity, systolic blood pressure, anti-diabetic drugs, HDL cholesterol, albumin, fasting plasma glucose, and eGFR, the association was still solid (OR = 2.02 1-SD, 95% CI 1.67–2.45, P < 0.0001)." (PMID 37875981, 2023). "Available studies suggest that poorly controlled laboratory parameters such as serum calcium and albumin as well as clinical characteristics (obesity, older age) or PROMs may have an influence on PD outcomes." (PMID 37747660, 2023). "However, for geriatric subjects, the most important factors were obesity, albumin, total bilirubin, alanine aminotransferase, serum ferritin, C-reactive protein and LDH." (PMID 36899318, 2023). "Furthermore, OG dogs in our study also presented higher ALP, triglycerides, albumin BChE, and lower lymphocytes (presenting a stress leukogram), thus further supporting the presence of hypercortisolism in dogs with obesity, as described in human obesity." (PMID 37505862, 2023). "Obesity is characterized by chronic low-grade inflammation and, as such, hepatic reprioritization of protein synthesis occurs, resulting in lower serum concentrations of albumin and prealbumin." (PMID 36986222, 2023). "Patients with pathological non-obesity showed low serum hemoglobin and albumin levels." (PMID 36324141, 2022). "Albumin is an antioxidant protein that decreases obesity-related inflammatory states." (PMID 36431836, 2022). "Our findings indicated that WWI may predict the incidence of albuminuria, and the management of obesity evaluated by WWI may alleviate the abnormal urinary albumin excretion." (PMID 36034904, 2022). "Recent studies have also evaluated non-coding RNA expression, sexual hormones, oxidative stress (uric acid, bilirubin, albumin) and metabolic biomarkers (metabolic syndrome, overweight/obesity, thyroid and liver function) in predicting BD and suicidality in individuals with bipolar disorder." (PMID 35740389, 2022). "Although detailed data on the nutritional status of patients were not evaluated in this study, several studies have shown a significant reduction in nutrition-related parameters, such as the obesity index, serum albumin, and hemoglobin in patients with esophageal cancer." (PMID 35768866, 2022). "Baseline demographics of study participants according to obesity and serum albumin categories." (PMID 34061848, 2021). "Similarly, previous study also reported that female gender, obesity, low serum albumin, DDLT, longer operation time, and more blood transfusions were associated with the development of post-LT AKI." (PMID 34442360, 2021). "It is plausible that this state of inflammation could lead to altered serum albumin levels among patients with obesity." (PMID 35010957, 2021).
Obesity (continued). "In addition, administration of AT1 blockers lead to a significant reduction in urinary albumin excretion, suggesting a strong link between obesity, RAAS and renal dysfunctions." (PMID 34268323, 2021). "In this study, we enrolled patients with type 2 DM, and found that all of the studied obesity-related indices (BMI, WHR, WHtR, LAP, BRI, CI, VAI, BAI, AVI, ABSI, and TyG index) were associated with albuminuria (defined as a urine albumin/creatinine ratio of ≥ 30 mg/g) in the patients." (PMID 34461808, 2021). "One possible hypothesis is obesity-induced glomerular hyperfiltration and increased urinary albumin excretion rate." (PMID 33228616, 2020). "Therefore, we evaluated the association between circulating albumin and macrophage content/activation in subcutaneous adipose tissue to characterize albumin as an indicator of obesity-induced inflammation." (PMID 30774722, 2019). "The mechanism was explained by hyperinsulinemia resulting from obesity that might increase the rate of albumin catabolism." (PMID 31498022, 2019). "In this study, complementary analyses delineated the role of plasma albumin in obesity and T2D." (PMID 30774722, 2019). "Similarly, for the obesity study there is a high correlation between c-peptide of insulin and insulin; total bilirubin and albumin; and hemoglobin, serum creatinine and uric acid." (PMID 29650030, 2018). "Since adaptive FSGS is characterized by relative lower level of proteinuria, relative normal serum albumin level and obesity, adaptive FSGS may account for a substantial portion in our registry." (PMID 29320993, 2018). "Similarly, insulin, c-peptide of insulin, albumin, uric acid, and vitamin D were identified as main variables for predicting obesity." (PMID 29650030, 2018). "In addition, performance on other quality, process, and intermediate indicators such as LDL-C, smoking, obesity, albumin-creatinine ratio, and estimated glomerular filtration rate (eGRF) were not included in these analyses." (PMID 28587646, 2017). "A higher total cholesterol, total bilirubin, and albumin level were found in the non-obesity group." (PMID 29108358, 2017). "This suggests glycated albumin is an unreliable marker of glycemic control in obesity." (PMID 27338619, 2016). "Decreased CML residue content of plasma protein in obesity has been explained as due to enlargement of adipose tissue mass in obesity and a contributory feature to this is likely decreased glycation of albumin due to the shift of albumin from plasma to interstitial fluid." (PMID 27338619, 2016). "We showed that severe obesity defined as BMI > 35 kg/m2 is not a risk factor for increased urinary albumin excretion in nondiabetic normotensive obese individuals." (PMID 26060835, 2015). "Moreover, consistent with previous studies, renal insufficiency (characterized by higher Alb/Cr and creatinine as well as lower serum albumin), obesity, and dyslipidemia were also related to an increasing of LVMI." (PMID 25924883, 2015). "On the other hand, other studies have suggested that the negative association of obesity with GA is due to abnormal albumin concentrations in obese subjects." (PMID 24586809, 2014). "Several researchers have suggested that declined serum albumin levels in obese patients may contribute to the inverse correlation between obesity and GA." (PMID 25013775, 2014). "In a previous study, obesity was related to an increased albumin excretion rate." (PMID 23594567, 2013). "However, hypertensive DM2 patients presented with the worst lipid profile, the greatest measures of obesity and the highest urinary albumin." (PMID 22429713, 2012). "Surprisingly, laminitis reported in this study was not linked to obesity but associated with insulin levels <20 mU/L, lower body weight, and glucose levels, along with higher concentrations of albumin, catalase, glucose, insulin, and IGF-1 compared to obese mares." (PMID 40901060, 2025).
Obesity (continued). "There is a strong link between obesity and TD, and several studies have shown a significant negative correlation between the degree of obesity and total testosterone, free testosterone, and bioavailable testosterone (free and bound to albumin), an association that is stable across age groups." (PMID 38915014, 2024). "Therefore, GNRI may be a more reliable indicator for detecting cognitive function in older adults than serum albumin levels and obesity‐related parameters." (PMID 39262164, 2024). "The serum albumin levels and metabolic phenotypes including fasting blood glucose, glucose tolerance tests, and glucose-stimulated insulin secretion were studied in db/db mice or diet-induced obesity mice treated with saline or young, undamaged, and ultrapure rMSA." (PMID 36747238, 2023). "Interestingly, the Pathological non-obesity group had the lowest serum albumin and hemoglobin, which suggested patients in this group might suffer from cardiac cachexia." (PMID 36324141, 2022). "Indeed, urine sodium, potassium, and albumin not adjusted for creatinine showed significant positive associations with obesity traits." (PMID 32008434, 2020). "This suggests that the explanation for decreased plasma glycated albumin in obesity with increased glucose exposure, as indicated by decreased glycated albumin/A1C ratio, may be due to a shift of albumin residence time from plasma to interstitial fluid in favour of the latter." (PMID 27338619, 2016). "An interesting observation from this study is that the mean BMI of the participants was 23.7 kg/m2 and that no increased risk of low-grade albuminuria or urinary albumin excretion was found among individuals having a BMI over 28 kg/m2, the level considered to mark obesity by Chinese standards." (PMID 26543300, 2015). "Similarly, obesity, specifically with central fat distribution, is commonly known to be associated with urinary albumin excretion independent of blood pressure and plasma glucose." (PMID 18230135, 2008). "There were significant differences (< 0.05) among different ePVS groups in gender, AKI, obesity and overweight, SBP, DBP, MAP, SPO2, WBC count, hematocrit, hemoglobin, albumin, ALP, AST, ALT, LDH, blood lipase, phosphate, AG, BUN, INR, SAPS II, and SOFA." (PMID 40301794, 2025). "The ML models were developed using a range of demographic and laboratory variables, including gender, age, overweight/obesity status, WBC, HCT, platelet count, AST, ALT, APTT, PT, fibrinogen, albumin, glucose, creatinine, and plasma sodium." (PMID 40337565, 2025). "Mediation analysis shows that lymphatic cells (LC) and albumin (ALB) partially mediate the link between brominated flame retardants and obesity." (PMID 40350287, 2025). "In contrast, haemoglobin, serum albumin, and PNI values were significantly lower in groups with more severe obesity (p < 0.001 for all)." (PMID 41517522, 2025). "The mean cellular volume, serum phosphate, albumin, creatinine, HDL-cholesterol, amylase, lipase, iron, and SHBG levels were significantly lower among patients with obesity." (PMID 40463745, 2025). "ALB abundance was found increased in several samples including, platelets, SAT or SKM proteome of individuals with obesity compared to normoweight matching controls." (PMID 38703299, 2024). "Independent risk factors identified for post-hepatectomy wound complications include older age, obesity, the utilization of ALPPS as the surgical technique, and lower postoperative albumin levels." (PMID 39535576, 2024). "The relevant published data for all physiological parameters, including height, weight, haematocrit, serum albumin, AGP, and GFR, were within the range of individual prediction values, which validated the paediatric obesity population." (PMID 38675150, 2024). "The VOCAL–Penn score included 9 variables: age, obesity, ACLD etiology (MAFLD vs. others), ASA classification, albumin and bilirubin levels, platelet count, and two surgical variables (emergency and type of surgery)." (PMID 36676081, 2023).